HLA-C (major histocompatibility complex, class I, C)
Diseases named in the same sentence as HLA-C in open-access papers (continued):
Sharing a sentence is not in itself a finding about the gene and the disease.
Autoimmunity (95 papers, 2005 to 2026). The occurrence of an immune reaction against the organism's own cells or tissues. "The patient presented an autoimmunity-associated HLA haplotype (HLA-A*02/HLA-B*08/HLA-C*07/HLA-DRB1*03) and experienced an increase in activated CD8 T-cells along the treatment." (PMID 34200673, 2021). "HLA-C expression levels correlate with immune responses to pathogens and autoimmunity, and vary in an allele-specific manner across individuals." (PMID 28649982, 2017). "Risk alleles for HLA-B and HLA-C determine susceptibility to autoimmunity and inflammation." (PMID 38474281, 2024). "The study of HLA-C peptide binding stability is critical for understanding immune regulation and its implications in infectious diseases, cancer, and autoimmunity." (PMID 41459481, 2025). "Donor 5443 was unusual, in that this donor was homozygous for a total of 7 out of 9 HLA alleles: HLA-B, HLA-C, HLA-DRB1, DRB4, DQA1, DQB1 and DPA1, with specific HLA alleles more predisposed to autoimmunity." (PMID 36936963, 2023). "HLA-C*07 is a ligand for activating and inhibiting killer immunoglobulin-like receptors (KIR) expressed by natural killer cells, and αβ and γδ T cells, and it has been suggested that a defect in KIR binding to HLA-C*07 may account for the association of this HLA allele with autoimmunity." (PMID 28066418, 2016). "The continuous interactions between KIR2DS1 and self C2+ HLA-C molecules in resting state, however, leads to hypo responsiveness, so that the subset of KIR2DS1+ NK cells will be educated to be anergic in individuals who carry C2+ HLA-C allotypes, perhaps to avoid autoimmunity." (PMID 28695287, 2017). "Interestingly, the pathogenesis of autoimmune/autoinflammatory disorders, such as AS, BD, BSCR and Ps, seems to arise, at least in part, by the epistatic interaction between ERAP1 and a HLA class I molecules (HLA-B*27, HLA-B*51, HLA-A*29:02 and HLA-C*06:02, respectively)." (PMID 33348540, 2020).
COVID-19 (80 papers, 2020 to 2025). A disease caused by infection with severe acute respiratory syndrome coronavirus 2. "After multiple regression models, only HLA-C*01 alleles, which are common in northern Italy, were positively associated with COVID-19." (PMID 38667755, 2024). "Among 69 COVID-19 patients from Egypt, HLA-C*16 and HLA-C*17 were associated with COVID-19 severity, while HLA-C*7 and HLA-C*12 were associated with protection from death." (PMID 38667755, 2024). "It should be underlined that HLA-C*04:01 was correlated with an increased risk of severe COVID-19 in both Asians and Caucasians." (PMID 39768617, 2024). "HLA-C*03 was associated with high ferritin, which was associated with increased COVID-19 severity in the Saudi population." (PMID 38667755, 2024). "The HLA class I alleles HLA-A*02:01 and HLA-B*40:01, related to high COVID-19 vaccine response, were found, as well as HLA-A*03:01, HLA-B*08:01 HLA-B*18:01, and HLA-C*07:01 related to low vaccine response." (PMID 38637586, 2024). "A study with 82 COVID-19-infected Han individuals from Zhejiang found a statistically significant difference between HLA-C*07:29 in COVID-19 patients compared to controls; this allele was prevalent in COVID-19 patients." (PMID 38667755, 2024). "HLA-C*05:01, HLA-C*07:01, HLA-C*08:02, HLA-C*15:02, and HLA-C*17:01 were associated with COVID-19 protection." (PMID 38667755, 2024). "HLA-C*04:01 enhanced the COVID-19 risk significantly in an association analysis with age, gender, and body mass index (BMI) as covariates (p-value = 0.005)." (PMID 38667755, 2024). "For individual ethnicities, an association between HLA-C*04:01 and severe COVID-19 was presented in every group." (PMID 38667755, 2024). "There were more HLA-C*16 alleles (p = 0.02) found in COVID-19 patients compared to controls; nonetheless, all the p-values were insignificant after multiple comparisons adjustment." (PMID 38667755, 2024). "HLA-C*04:01 has also been found to be associated with a severe clinical course of COVID-19, with patients carrying this allele having twice the risk of requiring mechanical ventilation." (PMID 39450171, 2024). "In an Armenian population of 299 COVID-19-infected individuals, HLA-C*04 was associated with a risk of hospitalization." (PMID 38667755, 2024). "A study with 9373 COVID-19-infected individuals and 5943 controls in Spain showed that HLA-C*04:01 was linked with severe COVID-19 (p = 0.045)." (PMID 38667755, 2024). "COVID-19-infected individuals with HLA-C*04:01, whose disease diagnosis was determined by days with the ventilator, were statistically significant to increased risk of COVID-19 after Bonferroni’s correction (p = 0.0023)." (PMID 38667755, 2024). "In a study, with 435 mild to severely symptomatic individuals from Spain (n = 133), Germany (n = 135), Switzerland (n = 20), and the US (n = 147), HLA-C*04:01 has been shown to have a potential association with severe COVID-19." (PMID 38667755, 2024). "In another Spanish population, HLA-C*08:02 was associated with a reduced risk of COVID-19 (p = 0.024)." (PMID 38667755, 2024). "The first study found that HLA-B*44 and HLA-C*01 allele groups were associated with an increased incidence of COVID-19." (PMID 36718139, 2023). "Certain alleles, such as HLA-C*01C*03, B*08, A*25, B*44, B*51, and B*15:01, have been positively correlated with the incidence rate of COVID-19, while other alleles, such as HLA-B*18, B*14, and B*49, have shown negative correlation." (PMID 37048725, 2023). "HLA-C*01 and HLA-B*44 are potential molecular determinants in evaluating an individual’s risk of COVID-19, and genotyping of class I and II HLA in COVID-19 patients can identify individuals at a higher risk of a cytokine storm." (PMID 37048725, 2023). "Certain HLA haplotypes (e.g., HLA-DRB1*04:01) were found to be associated with severe SARS-CoV-2 infection, while other haplotypes containing HLA-C alleles from group C1 were frequently associated with mild COVID-19 cases." (PMID 40729168, 2023).
COVID-19 (continued). "This study described a biologically plausible potential association of HLA-C*04:01 with severe clinical course of COVID-19, as HLA-C*04:01 has fewer predicted binding sites for relevant SARS-CoV-2 peptides compared to other HLA alleles." (PMID 36615135, 2023). "An interesting trend was noted between the severity of COVID-19 and the HLA-C*04 (P = 0.0077) as well as HLA-B*35 (P = 0.0051) alleles." (PMID 37708194, 2023). "HLA-C*01 and HLA-B*44 are potential molecular determinants for evaluating an individual’s risk of COVID-19." (PMID 37048725, 2023). "In an ordinal logistic regression, we found that the HLA-C*04:01 association with COVID-19 severity retained its significance (P<0.033), despite controlling for HLA class I heterozygosity." (PMID 35185875, 2022). "Strikingly, both of those HLA class I variables, i.e., heterozygosity and SARS-CoV-2 peptide presenting ability, showed stronger associations to the HLA-C*04:01 allele than to the clinical manifestation of COVID-19." (PMID 35185875, 2022). "The DNA methylation analysis of immune-related genes has pointed out a CGI (chr6:31276242-31276526) associated with HLA-C that was hypermethylated (Δβ=0.05) in COVID-19 patients compared to controls." (PMID 36325330, 2022). "Particularly, the relationship between the age and HLA-C*04:01 mirrored the association between advancing age and the severity score of COVID-19, while that of HLA-B*51:01 was in the opposite direction." (PMID 35185875, 2022). "The frequency of this allele HLA-C*08:02 in the Spanish population is 5.3%, which meant that it was 3.5-fold more prevalent in the group of individuals with mild COVID-19 of our cohort." (PMID 35960731, 2022). "Other studies also suggested increased risk of severe clinical course of COVID-19 in carriers of HLA-C*04:01." (PMID 36094909, 2022). "In contrast, we found that HLA-C*04:01 allelic-load contributes to the risk for the severe COVID-19 independently from age and classical HLA variables." (PMID 35185875, 2022). "In contrast, the HLA-B*38 and HLA-C*06 alleles, both analyzed in the same 4 articles (5 studies), were associated with risk for the most severe form of COVID-19 (OR = 1.64, 95% CI 1.03–2.60 and OR = 1.31, 95% CI 1.00–1.72, respectively)." (PMID 35793369, 2022). "In contrast, HLA-C*04:01 and -C*07:01, both linked to severe and/or critical COVID-19 presentations in our cohort, ranked 16 and 17th on this scale with only eight of these epitopes each (p = 0.0030)." (PMID 35960731, 2022). "The frequency of associations between HLA-C*08 or -C*12 alleles was significantly higher in individuals with mild COVID-19 (33.3%) than in individuals with critical COVID-19 (8.1%) (p = 0.0008; pc = 0.0088)." (PMID 35960731, 2022). "The comparison of HLA-C*04:01 frequency between subgroups and 2,781 Armenian controls revealed a significant incidence of HLA-C*04:01 deficiency in asymptomatic COVID-19." (PMID 35185875, 2022). "These comparative data indicate that the association between HLA-C*04:01 and COVID-19 is so substantial that it also drives a decrease in HLA I heterozygosity in severe cases." (PMID 35185875, 2022). "DNA methylation analysis in CpG sites associated with HLA-C gene in COVID-19 patients vs controls and asymptomatic vs symptomatic COVID-19 patients." (PMID 36325330, 2022). "Based on our observations, we developed a prediction model involving demographic variables and HLA-C*04:01 allele for the identification of potential cases with the risk of hospitalization (the area under the curve (AUC) = 86.2%) or severe COVID-19 (AUC =71%)." (PMID 35185875, 2022). "To elucidate the association mechanism of the HLA-C and COVID-19 severity, we compared the frequency distribution of the HLA-C*04:01 allele in the three clinical subgroups with a representative cohort of the Armenian population." (PMID 35185875, 2022).
COVID-19 (continued). "Our finding on the association between HLA-C*04:01 genomic quantity and COVID-19 severity is consistent with some previous reports of cross-sectional studies, involving Indian, German and USA (multiethnic) cohorts." (PMID 35185875, 2022). "In another study with 82 patients with COVID-19, a significantly higher frequency of the HLA-C*07:29 and HLA-B*15:27 alleles were found in patients with COVID-19 when compared with healthy individuals." (PMID 35062298, 2022). "Another study of Chinese patients with COVID-19 reported that the HLA-A*11:01, HLA-B*51:01 and HLA-C*14:02 alleles were significantly associated with severe disease or worse outcome." (PMID 34344463, 2021). "Equally interesting is the study that reported the distribution of HLA allele frequencies in 82 Chinese individuals with COVID-19 and identified HLA-C*07:29 and HLA-B*15:27 and HLA-B as statistically significant." (PMID 34344463, 2021). "After applying a multiple regression model to eliminate confounding factors, only the HLA-C*01 and HLA-B*44 alleles, which are present with a higher frequency in the northern regions of Italy, remained positively associated with COVID-19." (PMID 34344463, 2021). "We observed that the HLA-A*11:01:01:01 [Pc = 0.013, OR = 2.26 (1.27–3.91)] allele and HLA-C*12:02:02:01-HLA-B*52:01:01:02 [Pc = 0.020, OR = 2.25 (1.24–3.92)] haplotype were significantly associated with the severity of COVID-19." (PMID 33968060, 2021). "In the HLA association studies, HLA-A*11:01:01:01 [Pc = 0.013, OR = 2.26 (1.27–3.91)] and HLA-C*12:02:02:01-HLA-B*52:01:01:02 [Pc = 0.020, OR = 2.25 (1.24–3.92)] were found to be significantly associated with the severity of COVID-19." (PMID 33968060, 2021). "Each of HLA-A*11:01:01:01 and HLA-C*12:02:02:01 and HLA-B*52:01:01:02 were found to be independently associated with severity of COVID-19." (PMID 33968060, 2021). "According to the results, the prevalence of the HLA-C*01 and HLA-B*44 alleles are predictive of the incidence of COVID-19 in the different Italian regions and therefore confer susceptibility to SARS-CoV-2 infection." (PMID 33343579, 2020). "Conclusions: we demonstrated that allele frequency of HLA-C*05 and the distribution pattern with its receptor KIR2DS4fl strongly correlated with COVID-19 mortality." (PMID 33233780, 2020). "Our study has identified HLA-C*05 as the allele most strongly correlating with the risk of deaths due to COVID-19 at a global level." (PMID 33233780, 2020). "The role of HLA-C-restricted antigen-specific CTLs in COVID-19 and its association with disease progression is not well understood, although it is reported that some HLA-C allotypes are associated with COVID-19 severity." (PMID 40877317, 2025). "Moreover, in another review, HLA-C*05:01 was associated with a higher risk of severe COVID-19 and death in multiple populations, including Spain." (PMID 39336433, 2024). "In another study, HLA-C*07:01 was linked to a decreased risk of symptomatic COVID-19." (PMID 38667755, 2024). "HLA-C*05:01 was significantly associated with the risk of COVID-19 death." (PMID 38667755, 2024). "Additionally, a potential positive association of HLA-C*05:01 with neurological involvement was observed, an allele associated with COVID-19 mortality." (PMID 39835139, 2024). "In addition, another study with 92 COVID-19-infected individuals of 15 different nationalities with varying severity from the United Arab Emirates also observed a significant association between HLA-C*04 and COVID-19 severity (p = 0.0077)." (PMID 38667755, 2024). "HLA-C*14:02 allele was significantly predisposed to the worst outcomes in COVID-19 patients." (PMID 39450171, 2024). "However, in regard to HLA and the risk of severe COVID-19 course, our observations of the significance of HLA-C*04:01 are consistent with several other studies, including those conducted in Spanish, Armenian, Indian, and German populations." (PMID 39768617, 2024).
COVID-19 (continued). "Importantly, the association of HLA-C*04 allele to the severity of COVID-19 has previously been observed in Indians and South Asian (India, Pakistan, and Bangladesh) patients." (PMID 37708194, 2023). "Our results revealed that the hiPSC-CM line THTC-09 (HLA-A*33:03, HLA-B*58:01, HLA-C*03:02, and HLA-DRB1*03:01) was more susceptible to SAR-CoV-2 infection which correlated with the high level of ACE2 receptor expression." (PMID 35745684, 2022). "However, the HLA-C*04:01 association with COVID-19 manifestation is rather in concert with female gender and older age." (PMID 35185875, 2022). "Importantly, to our knowledge, this is the first study that describes a relationship between the presence of specific HLA-C alleles and the different presentations and prognosis of COVID-19." (PMID 35960731, 2022). "Furthermore, a study in China showed that HLA-C*07:29 and HLA-B*15:27 were more frequently present in COVID-19 patients; however, these alleles are rare in the Chinese population." (PMID 35745684, 2022). "The HLA-C*12:03 allele, linked to mild COVID-19 presentation in our study, contained the second highest number of verified epitopes, i.e., 65 (p <0.001, Fisher exact test), among 20 HLA-C alleles (26 ± 19 epitopes, mean ± standard deviation) in abundant SARS-CoV-2 proteins." (PMID 35960731, 2022). "Moreover, specific HLA-C*08:02 or -C*12:03 alleles were more frequent in 31.3% of individuals with mild COVID-19, in comparison with 3.2% (p = 0.0001; pc = 0.0010) of individuals with critical disease." (PMID 35960731, 2022). "We found that the association of HLA-C*04:01 genotype with the age in the COVID-19 cases was secondary to the association between the genotype and the COVID-19 severity characteristics (HLA-C*04:01 association with age conditioned for the disease severity, P=0.13)." (PMID 35185875, 2022). "Consistently to our results, Warren and Birol also report that the high prevalence of HLA-C*04:01 allele may predispose to severe COVID-19 in patients with a white ethnic background, female gender and advanced age (≥65 years old)." (PMID 35185875, 2022). "Initial reports from China and Europe described the association of certain alleles with COVID-19 such as HLA-C*07:29 and B*15:27 the prevalence of which was increased in COVID-19 patients or DRB1*15:01, -DQB1*06:02, and -B*27:07, the prevalence of which was increased in a cohort of Italian patients." (PMID 34685388, 2021). "We studied the association between class I MHC, HLA-A, -B and -C, and the risk of deaths due to COVID-19 at a worldwide level and have identified HLA-C*05 as a potential candidate that may influence mortality." (PMID 33233780, 2020). "Amongst them, HLA-C*05 was the most influential in increasing the risk of death due to COVID-19." (PMID 33233780, 2020). "In spite of genetic association data, a similar role of HLA-C in severe COVID-19 is yet unknown." (PMID 35185875, 2022). "Besides, the HLA-B*38 and HLA-C*06 alleles were associated with risk for severe COVID-19." (PMID 35793369, 2022). "However, screening for HLA-C genotype in patients from the populations, in which HLA-C*04:01 is a risk allele for the severe COVID-19, in addition to demographic variables, may support strategic clinical management of the disease." (PMID 35185875, 2022). "Thus, HLA-C*04:01 association with advancing age was specific to the patients and rather evolved from the allele precipitation in subgroups of mild/moderate and severe COVID-19 cases with a relatively higher average age." (PMID 35185875, 2022). "Therefore, the presence of more stable HLA-C alleles of group C1 in individuals with mild COVID-19 could contribute to their more efficient immune response, which was characterized by a higher cytotoxic activity against SARS-CoV-2 infected cells." (PMID 35960731, 2022).